STAT3 (signal transducer and activator of transcription 3)
Diseases named in the same sentence as STAT3 in open-access papers (continued):
Sharing a sentence is not in itself a finding about the gene and the disease.
cancer (continued). "Biochemical studies and genetic knockout mice models have indicated that two transcription factors, signal transducer and activator of transcription 3 (STAT3) and NF-κB, are the major factors associated with inflammation related to cancer." (PMID 33917793, 2021). "Cirsiliol, luteolin, and carnosol were identified from the methanol extract of Silvia officinalis as inhibitors of STAT3 signaling and the effects of these three compounds on STAT3 protein or growth inhibition on cancer cells was compared." (PMID 33392396, 2021). "It selectively inhibits growth of DU145 and MDA-MB-468.It inhibits JAK-STAT signaling pathway by attenuating JAKs activity and blocking STAT3 signaling (IC50 = 10.6 μM) in cancer cells." (PMID 33494352, 2021). "The JAK/STAT3 pathway has been broadly described as a vital signaling pathway involved in cancer cell biology." (PMID 34867344, 2021). "In this study, we elucidated the function of MARCH8 in cell survival, tumorigenesis, and metastasis in breast cancer, in which CD44 and STAT3 are known to contribute to the phenotypic functions mediated by cancer stem cells." (PMID 34067416, 2021). "Several crucial signalling pathways essential for the establishment of cancers such as STAT-3, NF-κB, PI3k/Aκt, JNK/p38-MAPK, TGF-ß/SMAD, Smac/DIABLO, p-IκB etc., are regulated by these two phytochemicals." (PMID 35069196, 2021). "STAT3 has clear roles in driving cancer progression and therapy resistance but rather little has been described regarding the tumorigenic roles of IL-2819,21,51–53." (PMID 33526787, 2021). "Beyond their important regulatory functions in immune response, STAT3 and NFκB family members are ubiquitously expressed in most types of cancer and involved in tumorigenesis, progressions and metastasis." (PMID 34018320, 2021). "STAT3 is activated in many forms of cancer, resulting in the proliferation of cancer cells and, through the effect of STAT3 on its target genes, immunosuppression." (PMID 34299488, 2021). "When cytokines are out of regulation, the potential cancer-promoting potential of STAT3 as a proto-oncogene will continue to be expressed in cells to promote tumorigenesis." (PMID 34326876, 2021). "Signal transducer and activator of transcription 3 (STAT3) is a transcription factor that can regulate the occurrence and progression of cancer." (PMID 34222329, 2021). "Its functions included inhibition of IL-6R/STAT3 signaling by binding to IL-6R mRNA in cancer cells as well as inhibition of the IL-6 molecule in TAMs by CPEB3." (PMID 34944712, 2021). "In an osteosarcoma model, apatinib suppresses the invasion and migration of cancer cells and the expression of PD-L1 by targeting STAT3 to inhibit the EMT." (PMID 33722297, 2021). "STAT3 plays an important role in cancer progression as a driver oncogene and acquired resistance of targeted therapies as an alternatively activated pathway." (PMID 33391507, 2021). "On the other hand, miRNAs such as miRNA-551b-3p can induce STAT3 signaling in enhancing the growth and metastasis of cancer cells." (PMID 33670518, 2021). "MiRNA-124 is a new emerging miRNA in cancer chemotherapy that its upregulation down-regulates oncogenic signal transducer and activator of transcription 3 (STAT3) pathway to promote CP sensitivity." (PMID 33921908, 2021). "In mouse models of cancer, STAT3 activation in hepatocytes is necessary for the acute phase response." (PMID 34202272, 2021). "Given the importance of STAT3 in cancer, STAT3 palmitoylation is likely to play a significant role in cancer too." (PMID 34803494, 2021). "Another important group of proteins activated by extracellular signals transmitted by RTKs and involved in cancer progression and survival are signal transducers and activators of transcription (STATs), in particular STAT3 and STAT5." (PMID 34830951, 2021). "Growing evidences suggested that aberrant activation of STAT3 induces malignant progression of cancer." (PMID 34059647, 2021).
cancer (continued). "UPR regulates, for example, the activation of molecular pathways such as NF-kB and STAT3 that, among other functions, promote the release of cytokines and affect cancer cell survival as well as immune response." (PMID 33513694, 2021). "This is consistent with previous studies showing that ROS activated STAT3 signaling in various cancers." (PMID 34372858, 2021). "Strikingly, they found HIV-1 integration immediately upstream of the first intron of STAT3 (in five cancer tissues from three participants) and LCK (in three tissues from two participants), in the same transcriptional orientation as the host gene." (PMID 34578439, 2021). "Relative balance between STAT1 and STAT3 levels in cancer cells determines two different dichotomous states: (i) an apoptosis progression and (ii) an anti-apoptosis state (inactivation of cell death program)." (PMID 34631119, 2021). "Plasma-treated osteosarcoma showed an initiation in the apoptotic pathway by reducing phosphorylation in the AMPK or STAT3 pathways, which had an inhibitory effect on cancer cells' growth." (PMID 35284036, 2021). "YC-1, an anti-cancer drug, induced cancer cell death that can be reversed by overexpression of STAT3." (PMID 34948424, 2021). "Previous reports have stated that the SOCS3/JAK2/STAT3 axis modulates the occurrence and development of various cancers." (PMID 34388111, 2021). "Here we report that phosphorylation of STAT3 regulates V-ATPase expression in cancer cells thus promote anoikis resistance." (PMID 34234852, 2021). "ARG1, an enzyme constitutively expressed in PMNs and stored within intracellular granules, is a downstream target of activated STAT3, and in circulating MDSCs from cancer patients, STAT3 controls the immune suppressive activity." (PMID 35069595, 2021). "The activation of these two pathways results in the stimulation of STAT3, transcription factors, mainly NF-κB, and signal transducer in cancer cells." (PMID 33917793, 2021). "Many signaling pathways, including IL-6/STAT3 (interleukin-6/signal transducer and activator of transcription 3), play crucial roles in cancer initiation and progression." (PMID 34901003, 2021). "The recent, reports on ouabain exerts its cytotoxic effects against various cancer cells by antagonizing the expression of STAT3." (PMID 34572488, 2021). "The sustained activation of STAT3 and NF‐kB ultimately leads to stimulation of pro‐survival, proliferative, and angiogenesis‐related genes in cancer." (PMID 33634982, 2021). "The activation of STAT3 contributes to cancer cell proliferation, dedifferentiation, invasion, and angiogenesis." (PMID 34502158, 2021). "STAT3 is widely studied in the field of cancer because the aberrant and persistent activation of STAT3 has been found in various types of cancers." (PMID 34070281, 2021). "Future studies will be needed to investigate the role of the JAK2/STAT3 pathway in silencing STING function in human cancers." (PMID 33790360, 2021). "Particularly, STAT3 activation in patients biopsies in situ declines during cancer progression from preinvasive to invasive cancers in which pSTAT3(Tyr705) expression was low or absent." (PMID 34469022, 2021). "Niclosamide induce cell cycle arrest, growth inhibition and apoptosis in cancer cells by targeting multiple signaling pathways such as, Wnt/β-catenin, STAT3, mTOR, Notch signaling pathways and mitochondria metabolic pathways." (PMID 33632240, 2021). "Increasing evidence suggests that acetylation of STAT3 at K685 contributes to its oncogenic activity and that elevated acetylation of STAT3 at K685 has been detected in a variety of human cancers." (PMID 33491667, 2021). "This transition is implicated in the regulation of metastasis and cancer progression and is driven by the IL-6/JAK2/STAT3 pathway in lung and ovarian carcinomas." (PMID 34207510, 2021). "JAK/STAT3 (the Janus kinase/signal transducer and activator of transcription 3) pathway activation has been found in various cancers." (PMID 34938816, 2021).
cancer (continued). "CCL20 was the ligand of CCR6 and reported to be accountable for recruiting CD4+ T cells to promote STAT3 activation to foster cancer stemness." (PMID 33514440, 2021). "More recent studies revealed that the inhibitor in particular interferes with the mitochondrial function of STAT3, which was demonstrated in human cancer cell lines in vitro." (PMID 34440253, 2021). "STAT3 is often deregulated in several kinds of cancer, and functions as an oncogene in tumorigenesis." (PMID 33804548, 2021). "Both IL-6 and IL-8 can induce chemotactic activities and direct neutrophils and monocytes to inflammatory tissues, and both the IL-6/STAT3 and IL-8/STAT3 axes mediate malignancies, cancer stemness, and immune suppression." (PMID 34063134, 2021). "Among these, IL-6 and its intracellular mediator STAT3 have clear links to PCa progression, as they do with other cancer types." (PMID 33808059, 2021). "One of the key mechanisms by which STAT3/NFκB signaling promotes cancer stemness is through their negative regulation of let-7 miRNAs." (PMID 34572067, 2021). "The activation and interaction between STAT3 and NF-κB play vital roles in the control of the communication between cancer cells and inflammatory cells." (PMID 34443375, 2021). "STAT3 target gene products have been reported to be entangled with the migration and invasion of cancer cells." (PMID 34771643, 2021). "It was well demonstrated that STAT3 signaling is a regulator of PD-L1 expression in mouse models and in cancer cell lines." (PMID 34572782, 2021). "EZH2 binds to STAT3, which leads to enhanced STAT3 activity via the increased tyrosine phosphorylation of STAT3 in cancer stem cells (CSCs)." (PMID 33823894, 2021). "As cancer cells can exhibit a reservoir of highly active STAT3, it seems as though STAT3 can act as the essential director of the required fueling operations for cells that are carrying out extreme survival activities." (PMID 33544704, 2021). "The Janus Kinase/Signal Transducer and Activator of Transcription 3 (JAK/STAT3) signaling pathway is important in various types of cancer." (PMID 34568031, 2021). "Considering that, to date, the vast majority of STAT3-targeted cancer therapeutic approaches focus only on its canonical functions, our findings imply mitochondrial STAT3-specific transcriptional activity as a significant molecular mechanism to be targeted." (PMID 34473253, 2021). "Given the importance of STAT3’s varied roles in cell metabolism and survival, STAT3 inhibitors have been considered as novel modes of cancer therapy." (PMID 33544704, 2021). "Signal transducer and activator of transcription 3 (STAT3) is a widely known protein which plays important roles in many diseases, including cancer development." (PMID 32960462, 2021). "For example, YTHDF1 expression had a strong association with STAT1 in Th1 cells, STAT6 in Th2 cells, STAT3 in Th17 cells, STAT5B in Treg cells, BCL6 in Tfh cells, and IRF5 in M1 macrophages in most cancer types." (PMID 34026603, 2021). "It’s well established that STAT3 activates numerous downstream signaling pathways involved in the pathogenesis of cancers." (PMID 34372858, 2021). "STAT3 plays important roles in cancer development and progression, and its expression was associated with shorter survival of patients with CCA." (PMID 34745255, 2021). "Reciprocally, MDSCs promote the stemness and mesenchymal properties of cancer cells through NOTCH/STAT3 signaling, forming a positive feedback loop with crosstalk between MDSCs and CSCs." (PMID 34235155, 2021). "Recent reports have shown that STAT3‐mediated lipid metabolism also plays essential role in cancer progression." (PMID 34766135, 2021). "The STAT3 signaling was activated in many cancers, its activation has been found to promote HCC progression." (PMID 34899687, 2021). "Taken together, STAT3 is a target for cancer therapy, and STAT3 inhibitors represent potential therapeutic candidates for the treatment of OS." (PMID 33382511, 2021).
cancer (continued). "We report that LINC00511, as a competitive endogenous RNA (ceRNA) of miR-625-5p, plays a cancer-promoting role in GC via targeting miR-625-5p, which in turn increases the expression of signal transducers and activators of transcription 3(STAT3)." (PMID 34224294, 2021). "This study discovered that hesperidin prevents IFN-γ-induced PD-L1 protein expression by inactivating STAT1/STAT3 signaling in OSCC cancer cells, contributing to tumors’ immune evasion." (PMID 34500779, 2021). "Evidence has supported the critical role of STAT3 singling in the migration and invasion of cancer cells." (PMID 34589421, 2021). "Through TLR activation, ovarian cancer exosomes can also induce IL-6 production in monocytes, which in turn activates the STAT3 pathway in immune cells, stromal cells, and tumor cells, thereby supporting immune escape of cancer cells." (PMID 34485600, 2021). "Given that STAT3 is frequently activated in NSCLC and controls major cancer properties, STAT3 has been considered a promising target for the treatment of NSCLC." (PMID 34068421, 2021). "Blockade of CAFs-LRG1 signaling cascade either by inhibitor or siRNA targeting JAK2/STAT3 axis can effectively attenuate migration and invasion of cancer cells induced by CAFs." (PMID 34930899, 2021). "STAT3 signaling pathway is a key molecular mechanism involved in a variety of cancer metastasis and tumorigenesis." (PMID 34638797, 2021). "Conversely, inhibition of the JAK/STAT3 signaling pathway slows cancer cell growth and induces apoptosis in various cancers." (PMID 34721022, 2021). "To test the positive feedback loop between miR-21-5p and STAT3 documented in other diseases, such as cancer, we inhibited the expression of miR-21-5p in A549 cells and LFs derived from the BAL of patients with and without CLAD." (PMID 33804639, 2021). "Histone methyltransferase SET9, a histone-modifying enzyme, is capable of methylating STAT3 on K140, leading to modulation of transcriptional activation of target genes in A4 cancer cells." (PMID 34642818, 2021). "Previous cumulative studies have found that increased expression of IL-6 stimulates overactivation of JAK/STAT3 signals and leads to poor prognosis in cancer patients." (PMID 34745261, 2021). "Many STAT3 inhibitors have gained momentum in clinical trials towards the treatment of various cancers." (PMID 34771643, 2021). "It is becoming evident that there is a role for interleukin-6 in inflammation and carcinogenesis, through its downstream transcription factors, such as signal transducer and transcription 3 (STAT3), which stimulates cancer cell proliferation and migration." (PMID 33923292, 2021). "Accordingly, inhibition of STAT3 tyrosine phosphorylation in several cancer cells down-regulates glycolysis prior to leading to growth arrest and cell death." (PMID 33718197, 2021). "The decrease in STAT3 activity inhibits cancer cell growth, invasion, migration, cell-cycle progression and differentiation." (PMID 34771718, 2021). "On the contrary, cryptolepine down-regulated pro-cancer pathway reporters such as STAT3, NF-κB and c-Myc." (PMID 34078370, 2021). "LLL12 is a small molecule that we developed, and it has shown potent and selective inhibition of STAT3 activities in multiple cancer cells in vitro." (PMID 33411696, 2021). "Despite manifold consequences of excessive activation of STAT3 in cancer cells, STAT3 is responsible for accelerating proliferation, apoptosis resistance, angiogenesis, and metastasis." (PMID 34867344, 2021). "The phosphorylation of NF-κB and STAT3 increased in the cancer groups, especially in the Cd-Can group." (PMID 34876963, 2021). "With this review, we sum up the discoveries about phosphorylation, acetylation, and methylation, highlighting the discrepancies among several studies and the importance of targeting these PTMs to therapeutically target STAT3 in cancer." (PMID 34440160, 2021).
cancer (continued). "The IL6/JAK/STAT3/SIGNALING pathway has been proved that it was aberrantly hyperactivated in various types of cancer and had a strong relationship with poor clinical prognosis." (PMID 34712264, 2021). "Involvement of the signal transducer and activator of transcription 3 (STAT3), which is activated by the S1PR1 pathway in causing inflammation and cancer has also been explained." (PMID 34001212, 2021). "The proposed pathway elicits NLRP3 as a therapeutic target to reverse canonical STAT3 mediated mechanisms of cancer promotion." (PMID 34531850, 2021). "Although arsenic can modify the expression of several genes, and some oncogenes such as STAT3 and PSMD10 have been associated with malignant transformation of hepatocytes, our knowledge of arsenic’s targets and effects on cancer etiology are unclear." (PMID 34577085, 2021). "The importance of STAT3 activation for the ability of cancer cells to acquire resistance to radiation treatment emerges considering the downstream targets." (PMID 34141616, 2021). "In line with this, HIF-1α/p300/p-STAT3 axis is considered a therapeutic target to eradicate cancer progression." (PMID 34692527, 2021). "The current study provided the experimental evidence for STAT3 inhibition by ouabain in cancer cells." (PMID 34277430, 2021). "The IL6/JAK/STAT3 pathway is aberrantly hyperactivated in many types of cancer, and is important for human BC development as well as BC metastasis." (PMID 35087836, 2021). "Taken together, modulation of STAT3 levels should be further explored as a potential novel pharmaceutical modality for the treatment of breast cancer as well as other cancer types." (PMID 34488773, 2021). "For this pathway, enriched genes such as STAT3 can activate cancer after the interaction of cytokines and cell surface receptors, and regulation of the downstream and promote the proliferation and growth of gene expression." (PMID 33892676, 2021). "Several studies indicate that human cancers contain constitutively activated STAT-3 protein, which is also persistently active and mediates cellular transformation in many immortalized cell lines, acting as an oncogene." (PMID 34064419, 2021). "In this study, we confirmed the cytotoxic effects of ouabain on several cancer cell lines and found that ouabain decreased the expression of STAT3 and thus prevented the activation of STAT3 signaling." (PMID 34277430, 2021). "Downregulation and inhibition of STAT3 after PDT leading to apoptosis was observed in cancer cells treated with 5-aminolevulinic acid, 2-[1-hexyloxyethyl]-2devinyl pyropheophorbide-a and benzoporphyrin derivative." (PMID 34829932, 2021). "F. nucleatum has also been shown to upregulate the Toll-like receptor (TLR) signaling and activation, of cell cycle regulators STAT3 and cyclin D1, leading to the growth of cancer cells." (PMID 34299675, 2021). "Mechanistically, diHEP-DPA reduced the expression of TAM markers by inhibiting the NF-κB signaling pathway, and inhibited cancer stemness via the ROS/STAT3 signaling pathway." (PMID 34573091, 2021). "High expressions of stem-cell-specific molecules (Oct4, Nanog, and Sox2) regulated by STAT3 have been reported in several malignancies and are accompanied with the stem phenotype of cancer cells." (PMID 33807148, 2021). "Aberrant expression of Nanog, Oct4, and c-Myc, downstream proteins of the STAT3 signaling pathway, was found in several cancers and is accompanied with cancer stemness." (PMID 33807148, 2021). "Altogether, our data demonstrate an unreported role of STAT3 in mediating the upregulation of V-ATPase to promote anoikis resistance, thus provides an alternative option to target cancer metastasis." (PMID 34234852, 2021). "In this study, we examined the additive anti-proliferative effect of gefitinib on cancer cells treated by these three compounds and found that cirsiliol had unique characters in STAT3-responding signals among the three compounds." (PMID 33392396, 2021).